NUTF2 (nuclear transport factor 2)
Description:
Mediates the import of GDP-bound RAN from the cytoplasm into the nucleus which is essential for the function of RAN in cargo receptor-mediated nucleocytoplasmic transport. Thereby, plays indirectly a more general role in cargo receptor-mediated nucleocytoplasmic transport. Interacts with GDP-bound RAN in the cytosol, recruits it to the nuclear pore complex via its interaction with nucleoporins and promotes its nuclear import.
Synonyms: NTF-2; PP15; NTF2
Tractability: PROTAC: ubiquitination databases record sites on it; its protein half-life has been measured.
Gene: Protein-coding gene on chromosome 16 (67,846,867 to 67,872,569, forward strand). Ensembl gene ENSG00000102898.
Subcellular location: Cytoplasm, cytosol; Nucleus outer membrane; Nucleus, nuclear pore complex; Nucleus inner membrane; Nucleus, nucleoplasm
Gene Ontology:
Molecular function: identical protein binding; protein binding; small GTPase binding; structural constituent of nuclear pore; nuclear import signal receptor activity
Biological process: protein export from nucleus; protein import into nucleus; protein localization to nuclear pore; nucleocytoplasmic transport
Cellular component: cytosol; extracellular exosome; nucleoplasm; nuclear inner membrane; nuclear membrane; nuclear outer membrane; nuclear pore central transport channel; nuclear pore
Genetic constraint (gnomAD): Loss-of-function variants: 2 observed, 15.61 expected, observed/expected ratio (o/e) 0.13, 90% interval 0.051 to 0.4. The upper end of that interval is the gene's LOEUF score, 0.4, which puts it in group 1 of 6, group 1 being the genes least tolerant of losing a copy. Missense variants: 42 observed, 156.29 expected, observed/expected ratio (o/e) 0.27, 90% interval 0.21 to 0.35. Synonymous variants: 50 observed, 56.79 expected, observed/expected ratio (o/e) 0.88, 90% interval 0.7 to 1.11.
Homologues: Orthologues: chimpanzee NUTF2 (100% identical), dog NUTF2 (100% identical), guinea pig NUTF2 (100% identical), macaque NUTF2 (100% identical), mouse Nutf2 (100% identical), mouse Nutf2-ps1 (100% identical), rat Nutf2l1 (100% identical), rat AABR07018058.1 (94% identical), zebrafish nutf2 (92% identical), tropical clawed frog nutf2 (88% identical), pig NUTF2 (81% identical), Caenorhabditis elegans ran-4 (46% identical), and 2 more. Paralogues in human: NXT2 (27% identical), NXT1 (25% identical).
Diseases named in the same sentence as NUTF2 in open-access papers:
NUTF2 is named in the same sentence as 25 diseases in open-access papers, as found by Europe PMC text mining. Sharing a sentence is not in itself a finding about the gene and the disease. The quoted sentences say what the papers report.
glioma (5 papers, 2022). A benign or malignant brain and spinal cord tumor that arises from glial cells (astrocytes, oligodendrocytes, ependymal cells). "With respect to cancer, upregulation of NUTF2 was found in glioma tissues and overexpression of NUTF2 promoted migration and proliferation of glioma cells, indicating its oncogenic role in glioma." (PMID 35155261, 2022). "A study reported that LINC00173 plays an important oncogenic role in glioma by activating the miR-765/NUTF2 pathway." (PMID 35401659, 2022). "In tumor research, long noncoding RNA (lncRNA) LINC00173 could promote the development of disease by enhancing NUTF2 expression in glioma." (PMID 35155672, 2022). "In glioma, LINC00173 sponges miR-765 to upregulate the expression of NUTF2 expression, and NUTF2 overexpression further promotes the proliferation, migration, and invasion of glioma cells, suggesting that LINC00173 functions as a critical oncogenic lncRNA in glioma." (PMID 36497407, 2022).
melanoma (5 papers, 2019 to 2025). A malignant, usually aggressive tumor composed of atypical, neoplastic melanocytes. "In addition, NUTF2 was expected to provide a target for combination therapy as a novel treatment for cancers; in prostate cancer cells, it improved drug sensitivity and reduced cell proliferation; in melanoma, it downregulated factors that caused drug resistance." (PMID 35155672, 2022). "NUTF2 overexpression was examined to exhibit melanoma metastasis, cell proliferation, and increase apoptosis." (PMID 35155672, 2022). "To begin to address this question, we studied Nuclear Transport Factor 2 (NTF2) because its levels decrease during melanoma progression." (PMID 34880267, 2021). "An experiment in Xenopus laevis cells found that decreased level of NUTF2 may contribute to melanoma development through the regulation of cell nuclear size." (PMID 35155672, 2022). "Besides, the level of NUTF2 expression was downregulated and negatively correlated with nuclear size in melanoma tissue." (PMID 35155672, 2022). "Increasing NUTF2 levels plays a negative role in the progression of melanoma." (PMID 35155672, 2022).
breast carcinoma (4 papers, 2012 to 2023). "In our study, Lumina B tumors have higher NUTF2 expression than Lumina A. These results indicate that NUTF2 may play an important role in the progression and prognosis in breast cancer." (PMID 35155261, 2022). "Six of the 11 non-mitosis related genes were previously associated with poor survival in breast cancer patients: KRT17, MMP12, SLC7A5, SQLE, GABRP and PA2G4, but the remaining 5 had not been previously associated with cancer risk: CCDC86, NUP107, NUTF2, WASF1 and ELOVL6." (PMID 23077491, 2012). "By identifying ~104 complexoforms from 17 protein complexes, our nTDP approach revealed several molecular features of the breast cancer proteome, including EGFR-induced dissociation of nuclear transport factor 2 (NUTF2) assemblies that modulate ER activity." (PMID 37546719, 2023). "Altogether, these results support a new EGFR–ERα signaling crosstalk mechanism in breast cancer cells, where EGFR signaling dissociates NUTF2 dimers and alters the PTM code to modulate ER signaling and cell growth, along with other critical drivers of cancer growth and metabolism." (PMID 37546719, 2023).
diabetic retinopathy (3 papers, 2009 to 2022). "Early reports showed that NUTF2 engaged in protecting from diabetic retinopathy through depressing vascular endothelial growth factor (VEGF) expression." (PMID 35155672, 2022). "Other examples include lemur tyrosin kinase (LMTK2), and nuclear transport factor 2 (NUTF2) involved in cancer susceptibility and diabetic retinopathy, respectively." (PMID 21479260, 2011). "We performed human, animal, and in vitro studies to examine the potential role of nuclear transport factor 2 (NTF2) in conferring resistance to diabetic retinopathy (DR)." (PMID 19404486, 2009).
Alzheimer disease (1 paper, 2022). A progressive, neurodegenerative disease characterized by loss of function and death of nerve cells in several areas of the brain leading to loss of cognitive function such as memory and language. "Moreover, NUTF2 aggregation may alter nucleoplasm transport in nerve cells of Alzheimer's disease patients, leading to neuronal abnormalities and death." (PMID 35155672, 2022).
head and neck squamous cell carcinoma (1 paper, 2024). A squamous cell carcinoma that arises from any of the following anatomic sites: lip and oral cavity, nasal cavity, paranasal sinuses, pharynx, larynx, and salivary glands. "Another study by Li defined seven‐gene NET‐related signature, including ITGA5, NIFK, NUTF2, PDGFα, TNFRSF12, LINC00460 and LINC02454, for head and neck squamous cell carcinoma through the TCGA and ICGC cohorts (p‐value < 0.05)." (PMID 39730971, 2024).
cancer (10 papers, 2011 to 2024). A tumor composed of atypical neoplastic, often pleomorphic cells that invade other tissues. "It was known that DNA copy number amplification and methylation were the two underlying causes for NUTF2 upregulation in cancers." (PMID 35155261, 2022). "In most cancer types, NUTF2 expression was positively associated with infiltrated activated CD8+ T cell, central memory CD4+ T cell, gamma delta T cell, CD56bright/CD56dim NK cell and monocyte." (PMID 35155261, 2022). "Additionally, we explored the potential associations between copy number amplification and NUTF2 expression across the 33 types of cancers." (PMID 35155261, 2022). "By taking the pro-tumor role of MDSCs in these four types of cancers into consideration, NUTF2-mediated MDSC infiltration may be a crucial cause for its oncogenic effect." (PMID 35155261, 2022). "In the present study, we revealed that the expression of NUTF2 was evaluated in 19 types of cancers." (PMID 35155261, 2022). "We explored the genetic alterations of NUTF2 in TCGA pan-cancer atlas studies via the cBioPortal online resource." (PMID 35155261, 2022). "Compared with corresponding adjacent normal tissues, the expression of NUTF2 was significantly upregulated in 19 cancer types of TCGA." (PMID 35155261, 2022). "Further analysis suggested that the expression of NUTF2 expression was correlated with the infiltration of immune cells, such as CD8+ T cells, effector memory CD4+ T cells, and cancer-associated fibroblasts in kidney renal clear cell carcinoma." (PMID 35155261, 2022). "This pan-cancer analysis of NUTF2 provides a systemic understanding of its oncogenic role across different types of cancers." (PMID 35155261, 2022). "By taking the overexpression of NUTF2 in various types of cancers into consideration, we focused on the copy number amplification variation of the NUTF2 DNA fragment." (PMID 35155261, 2022). "Out of 33 types of cancers, 19 types had significantly different expression of NUTF2 between tumor and normal tissues." (PMID 35155261, 2022). "Our study comprehensively analyzed the oncogenic role of NUTF2 across various cancer types, and highlights the possibility of NUTF2 to serve as a cancer prognostic biomarker." (PMID 35155261, 2022). "We further investigated the prognostic significance of NUTF2 among the 33 different types of cancers." (PMID 35155261, 2022). "Previous studies indicated that high immune/stromal/ESTIMATE scores were significantly correlated with poor prognosis and advanced tumor grade in LGG, suggesting the cancer promoting role of NUTF2 via facilitating stromal and immune cell infiltration in LGG." (PMID 35155261, 2022). "Co-expression analysis results indicated that NUTF2 was positively correlated with the expression of these EMT markers among most types of cancers, especially in HNSC." (PMID 35155261, 2022). "Additional proteins with significant upregulated scores (BTF3, SNRPA, and NUTF2), which promote cancer in other types of malignances, also lead to lower survival probability in CLL patients, apart from BTF3 that seems to affect survival only during the initial days of disease development." (PMID 39202022, 2024). "The role of NUTF2 in cancer development is largely unknown and lacks systemic assessment across human cancers." (PMID 35155261, 2022). "However, the frequency of DNA amplification is relatively low in cancers, and other possible explanations for NUTF2 dysregulation need to be explored." (PMID 35155261, 2022). "In the present study, we conducted a pan-cancer analysis of NUTF2 based on the TCGA dataset." (PMID 35155261, 2022). "NUTF2 expression profile and prognostic significance were investigated among various human cancers." (PMID 35155261, 2022). "It was found that “anaphase-promoting complex-dependent catabolic process” and “protein binding” might be involved in the process of NUTF2 on cancer pathogenesis." (PMID 35155261, 2022).
cancer (continued). "In this study, we performed a pan-cancer analysis of NUTF2 in human cancers." (PMID 35155261, 2022). "It was found that the overall genetic alteration frequency of NUTF2 was relatively low in cancers." (PMID 35155261, 2022). "In addition, the heat map revealed positive correlations between NUTF2 expression and the top 5 genes in the vast majority of cancer types." (PMID 35155261, 2022). "However, few studies have explored the topic of NUTF2 with cancer." (PMID 35155672, 2022). "However, few studies have explored the relationship between NUTF2 and cancers." (PMID 35155672, 2022). "Second, further analysis has identified seven NET-related genes, including NIFK, LINC00460, NUTF2, and LINC02454, some of which are potentially predictive biomarkers for human cancers." (PMID 36225931, 2022). "However, the role of NUTF2 in other cancer types is largely unknown." (PMID 35155261, 2022). "The significant negative correlation between NUTF2 expression level and DNA methylation was identified in 25 types of cancers (FDR < 0.05)." (PMID 35155261, 2022). "In addition, we also analyzed the correlation between NUTF2 and the epithelial–mesenchymal transition (EMT) markers, Vimentin (VIM), TWIST1, Snail1 (SNAI1), Snail2 (SNAI2), Fibronectin 1 (FN1), and N‐cadherin (CDH2), which were widely accepted to be involved in cancer metastasis." (PMID 35155261, 2022).
tumor (9 papers, 2013 to 2025). "In addition, we also analyzed the relationship between NUTF2 expression and marker genes of immune cells, including monocyte, tumor-associated macrophage (TAM), M1 macrophage, and M2 macrophage." (PMID 35155261, 2022). "Additionally, the expression of TWIST1, SNAI1, FN1, and CDH2 also showed significant association with NUTF2, suggesting that NUTF2 may play a major tumor-promoting role in the Lumina A BRCA subtype." (PMID 35155261, 2022). "The correlations between NUTF2 expression and tumor infiltrated CD8+ T cell and B cell were confirmed." (PMID 35155672, 2022). "With tumor purity unregulated, the correlations further illustrated the possible role of NUTF2 in the regulation of tumor infiltrated CD8+ T cell and B cell." (PMID 35155672, 2022). "Compared with the adjacent normal tissues, the results indicated that NUTF2 expression was significantly upregulated in the tumor tissues." (PMID 35155672, 2022). "Besides, we found higher NUTF2 expression in different HNSCC subtypes as well as in paired comparisons of tumor tissue with normal tissue from the same patients." (PMID 35155672, 2022). "Meanwhile, survival analysis showed that NUTF2 could be an independent prognostic factor in several tumor types." (PMID 35155261, 2022). "Furthermore, the paired analysis, in which normal and tumor tissue come from same patient, showed a significant upregulation of NUTF2 expression in HNSCC." (PMID 35155672, 2022). "Our findings suggested that NUTF2 may participate in the immune regulation through regulating T/B cell receptor signaling pathways in the process of tumor oncology in HNSCC." (PMID 35155672, 2022). "Through using GSEA, we explored the mechanism that may be related to NUTF2 in the regulation of tumor immunity." (PMID 35155672, 2022). "The relationship between NUTF2 and tumor progression also remains unclear." (PMID 38584705, 2024). "NUTF2 expression was found to be highly correlated with MKI67 and PCNA in 27 tumor types including ACC, BLCA, and BRCA (P < 0.05)." (PMID 38402311, 2024). "In order to investigate the role of NUTF2 in regulating the interaction between tumor and immune cells, we used the TISIDB platform to dissect the correlation between NUTF2 expression and infiltrating immune cells." (PMID 35155261, 2022). "It was found that NUTF2 expression was significantly correlated with immune score, stromal score, and ESTIMATE score in several tumor types." (PMID 35155261, 2022). "In this study, the tumor immune infiltration analysis suggested negative correlations between NUTF2 expression and infiltrated T cell and B cell levels in HNSCC." (PMID 35155672, 2022). "Tumor immune infiltration analysis revealed a significantly negative correlation between NUTF2 expression and the level of tumor infiltrated CD8+ T cell and B cell, suggesting that NUTF2 may be involved in the immune regulation of HNSCC." (PMID 35155672, 2022). "Moreover, we discussed the prognostic value of NUTF2 in HNSCC by DFS analysis, which excludes patients who survive but relapse with HNSCC, offering patients a direct clinical benefit on tumor recurrence and can be a more valuable survival index." (PMID 35155672, 2022).
NUTF2 also shares sentences with these, for which no sentence is quoted: infection (4 papers); diabetic (2); prostate carcinoma (2); adenoma (1); bladder urothelial carcinoma (1); cholangiocarcinoma (1); colon adenocarcinoma (1); colorectal cancer (1); esophageal carcinoma (1); Insulin resistance (1); keratosis (1); lymph node metastasis (1); metastatic cancer (1); metastatic melanoma (1); schizophrenia (1); type 2 diabetes mellitus (1); virus infections (1).